RFT1 (RFT1 glycolipid translocator homolog)
Description:
Intramembrane glycolipid transporter that operates in the biosynthetic pathway of dolichol-linked oligosaccharides, the glycan precursors employed in protein asparagine (N)-glycosylation. The sequential addition of sugars to dolichol pyrophosphate produces dolichol-linked oligosaccharides containing fourteen sugars, including two GlcNAcs, nine mannoses and three glucoses. Once assembled, the oligosaccharide is transferred from the lipid to nascent proteins by oligosaccharyltransferases. The assembly of dolichol-linked oligosaccharides begins on the cytosolic side of the endoplasmic reticulum membrane and finishes in its lumen. RFT1 could mediate the translocation of the cytosolically oriented intermediate DolPP-GlcNAc2Man5, produced by ALG11, into the ER lumen where dolichol-linked oligosaccharides assembly continues. However, the intramembrane lipid transporter activity could not be confirmed in vitro (By similarity).
Synonyms: CDG1N; SLC76A1
Tractability: Antibody: UniProt predicts a signal peptide or a membrane-spanning region. PROTAC: ubiquitination databases record sites on it; its protein half-life has been measured.
Gene: Protein-coding gene on chromosome 3 (53,066,853 to 53,130,472, reverse strand). Ensembl gene ENSG00000163933.
Subcellular location: Endoplasmic reticulum membrane
Subcellular location (Human Protein Atlas): Vesicles
Pathways (Reactome):
Disease: Defective RFT1 causes CDG-1n
Metabolism of proteins: Biosynthesis of the N-glycan precursor (dolichol lipid-linked oligosaccharide, LLO) and transfer to a nascent protein
Gene Ontology:
Molecular function: glycolipid floppase activity; protein binding
Biological process: dolichol-linked oligosaccharide biosynthetic process; glycolipid translocation; protein N-linked glycosylation
Cellular component: endoplasmic reticulum membrane; membrane
Genetic constraint (gnomAD): Loss-of-function variants: 38 observed, 55.71 expected, observed/expected ratio (o/e) 0.68, 90% interval 0.52 to 0.89. The upper end of that interval is the gene's LOEUF score, 0.89, which puts it in group 3 of 6, group 1 being the genes least tolerant of losing a copy. Missense variants: 583 observed, 636.46 expected, observed/expected ratio (o/e) 0.92, 90% interval 0.86 to 0.98. Synonymous variants: 258 observed, 264.71 expected, observed/expected ratio (o/e) 0.97, 90% interval 0.88 to 1.08.
Gene-disease validity (ClinGen):
ClinGen rates the evidence that RFT1 causes each of these diseases.
RFT1-congenital disorder of glycosylation (autosomal recessive): Moderate.
Homologues: Orthologues: chimpanzee RFT1 (99% identical), macaque RFT1 (97% identical), dog RFT1 (91% identical), pig RFT1 (91% identical), guinea pig RFT1 (89% identical), mouse Rft1 (87% identical), rat Rft1 (87% identical), rabbit RFT1 (85% identical), zebrafish rft1 (64% identical), tropical clawed frog rft1 (57% identical), Drosophila melanogaster CG3149 (37% identical), Caenorhabditis elegans rfth-1 (28% identical).
Diseases named in the same sentence as RFT1 in open-access papers:
RFT1 is named in the same sentence as 11 diseases in open-access papers, as found by Europe PMC text mining. Sharing a sentence is not in itself a finding about the gene and the disease. The quoted sentences say what the papers report.
congenital disorder of glycosylation (2 papers, 2023 to 2024). Congenital disorder of glycosylation (CDG) is a fast growing group of inborn errors of metabolism characterized by defective activity of enzymes that participate in glycosylation (modification of proteins and other macromolecules by adding and processing of oligosaccharide side chains). "More than 30 congenital disorders of glycosylation (CDGs) are associated with this pathway, including RFT1-CDG which results from defects in the membrane protein Rft1." (PMID 39025454, 2024). "A homozygous missense variant p.Gly494Ser in exon 13 of the RFT1 gene was classified as a VUS for RFT1-congenital disorder of glycosylation (CDG) with autosomal recessive inheritance." (PMID 37712079, 2023).
developmental delay (1 paper, 2023). "RFT1-CDG was first recognised as a severe congenital disorder of N-linked glycosylation characterised by developmental delay, failure to thrive, myoclonic encephalopathy, seizures, and sensorineural hearing loss." (PMID 37712079, 2023).
cancer (4 papers, 2019 to 2025). A tumor composed of atypical neoplastic, often pleomorphic cells that invade other tissues. "Yeast RFT1 is homologous to human RFT1 and SEC61A1 and has been used to study congenital disorder of glycosylation type I and cancer." (PMID 40512775, 2025). "Targeting ALG14 or RFT1 led to HCC cell death in a consistent fashion, expanding a variety of cancer cell lines." (PMID 38927057, 2024). "In the end, CCT6A, UTP18, YRDC, RRP12, RFT1, NLE1, and DDOST were essential genes across pan-cancer including COAD cells." (PMID 31867042, 2019). "In addition, CCT6A, UTP18, YRDC, RRP12, RFT1, NLE1, as well as DDOST were essential genes across pan-cancer including COAD cells, and ACTG1 and RHOQ were less essential genes in cancer cells." (PMID 31867042, 2019). "Dependency score analysis by DepMap showed that ACTG1 and RHOQ were less essential across pan-cancer cells including COAD cell lines, and CCT6A, UTP18, YRDC, RRP12, RFT1, NLE1, as well as DDOST were essential across pan-cancer cells including most of COAD cell lines." (PMID 31867042, 2019).
RFT1 also shares sentences with these, for which no sentence is quoted: Ataxia (1 paper); Failure to thrive (1); fructose intolerance (1); genetic disorders (1); infection (1); neurodevelopmental disorder (1); neurological disease (1); Sensory neuropathy (1).